RPL37A (ribosomal protein L37a)
Description:
Component of the large ribosomal subunit. The ribosome is a large ribonucleoprotein complex responsible for the synthesis of proteins in the cell.
Synonyms: L37A; eL43
Tractability: Small molecule: an approved drug acts on it; a structure with a bound ligand is known; a high-quality ligand is known. PROTAC: ubiquitination databases record sites on it; its protein half-life has been measured; a small molecule that binds it is known. Other modalities: a drug acting on it is in phase 2 or 3 trials.
Target class: Other cytosolic protein
Gene: Protein-coding gene on chromosome 2 (216,498,797 to 216,579,180, forward strand). Ensembl gene ENSG00000197756.
Subcellular location: Cytoplasm
Subcellular location (Human Protein Atlas): Cytosol; Endoplasmic reticulum
Pathways (Reactome):
Metabolism of proteins: Eukaryotic Translation Termination; Formation of a pool of free 40S subunits; GTP hydrolysis and joining of the 60S ribosomal subunit; L13a-mediated translational silencing of Ceruloplasmin expression; PELO:HBS1L and ABCE1 dissociate a ribosome on a non-stop mRNA; Peptide chain elongation; Ribosome Quality Control (RQC) complex extracts and degrades nascent peptide; SRP-dependent cotranslational protein targeting to membrane; ZNF598 and the Ribosome-associated Quality Trigger (RQT) complex dissociate a ribosome stalled on a no-go mRNA
Metabolism of RNA: Major pathway of rRNA processing in the nucleolus and cytosol; Nonsense Mediated Decay (NMD) enhanced by the Exon Junction Complex (EJC); Nonsense Mediated Decay (NMD) independent of the Exon Junction Complex (EJC)
Cellular responses to stimuli: Response of EIF2AK4 (GCN2) to amino acid deficiency
Developmental Biology: Regulation of expression of SLITs and ROBOs
Disease: Viral mRNA Translation
Metabolism: Selenocysteine synthesis
Gene Ontology:
Molecular function: protein binding; RNA binding; structural constituent of ribosome
Biological process: cytoplasmic translation; negative regulation of myoblast fusion; spermatogenesis; striated muscle contraction; translation
Cellular component: cytoplasm; cytosolic large ribosomal subunit; cytosolic ribosome; extracellular exosome; focal adhesion; nucleus; cytosol; ribosome
Genetic constraint (gnomAD): Loss-of-function variants: 5 observed, 12.11 expected, observed/expected ratio (o/e) 0.41, 90% interval 0.22 to 0.87. The upper end of that interval is the gene's LOEUF score, 0.87, which puts it in group 3 of 6, group 1 being the genes least tolerant of losing a copy. Missense variants: 64 observed, 98.68 expected, observed/expected ratio (o/e) 0.65, 90% interval 0.53 to 0.8. Synonymous variants: 38 observed, 34.12 expected, observed/expected ratio (o/e) 1.11, 90% interval 0.86 to 1.46.
Homologues: Orthologues: guinea pig RPL37A (100% identical), mouse Rpl37a (100% identical), pig RPL37A (100% identical), rabbit RPL37A (100% identical), rat Rpl37al2 (99% identical), tropical clawed frog rpl37a (97% identical), zebrafish RPL37A (97% identical), macaque RPL37A (78% identical).
Diseases named in the same sentence as RPL37A in open-access papers:
RPL37A is named in the same sentence as 19 diseases in open-access papers, as found by Europe PMC text mining. Sharing a sentence is not in itself a finding about the gene and the disease. The quoted sentences say what the papers report.
breast carcinoma (5 papers, 2011 to 2023). "Jag2 has been associated with adenomas, pancreatic and breast cancer, Rpl37a with nasopharyngeal carcinoma cell lines, and the rest with glioblastoma." (PMID 21649900, 2011). "In breast cancer, high Rpl37a expression has been associated with response to treatment and good prognosis and has been suggested as a biomarker while its role in inflammation remains unclear." (PMID 35720411, 2022). "In breast cancer, RPL37A expression, in conjunction with metastases suppressor 1 (MTSS1), as well as SET and MYND domain-containing protein 2 (SMYD2), were shown to predict the response of breast cancer patients to neoadjuvant doxorubicin and cyclophosphamide." (PMID 36008952, 2022).
glioblastoma (2 papers, 2011 to 2022). The most malignant astrocytic tumor (WHO grade IV). "RPL37A (named UOB-COL-11 in our study) has also been found to be upregulated in high grade astrocytomas and to have a general association with lifetime and overall glioblastoma survival (p-value < 0.05 in both cases)." (PMID 36008952, 2022). "We found that above-median levels of RPL37A in CRC patients significantly correlated with improved disease-free survival (p = 0.0055), supporting the belief that RPL37A may play a role in cell death, as suggested in glioblastoma." (PMID 36008952, 2022).
osteosarcoma (2 papers, 2022). A usually aggressive malignant bone-forming mesenchymal neoplasm, predominantly affecting adolescents and young adults. "RPL37A has been reported as a prognostic risk gene for osteosarcoma, which is consistent with the results of this study." (PMID 36569871, 2022).
ovarian endometrioid adenocarcinoma (2 papers, 2022 to 2025). An endometrioid adenocarcinoma arising from the ovary. "In another study, a comparison of five healthy control ovarian samples with three ovarian endometrioid adenocarcinoma samples demonstrated the least variation in levels of PPIA, RPL37A (Ribosomal protein L37a), and RPS17 (Ribosomal protein S17) among the investigated HKGs." (PMID 40943534, 2025).
Alzheimer disease (1 paper, 2024). A progressive, neurodegenerative disease characterized by loss of function and death of nerve cells in several areas of the brain leading to loss of cognitive function such as memory and language. "The down-regulated DEGs in NM versus NN were primarily focused on ribosome (about 26 DEGs, including RPL37A and RPL35), Alzheimer’s disease (about 20 DEGs, including SNCA and COX8A), and retrograde endocannabinoid signaling (about 6 DEGs, such as NDUFA1 and GNG5)." (PMID 38660519, 2024). "The DEGs that were down-regulated in DM compared to NM were primarily related to the ribosome (about 23 DEGs, including RPL37A and RPS11), Alzheimer’s disease (about 19 DEGs, including APC2 and COX8A), and non-alcoholic fatty liver disease (about 11 DEGs, such as SNCA and COX8A)." (PMID 38660519, 2024).
colorectal cancer (1 paper, 2023). A primary or metastatic malignant neoplasm that affects the colon or rectum. "Because FIRΔexon2 is detected in colorectal cancer tissues, the expressions of RPL30, RPL37A, RPL38, RPS14, and RPS29 mRNAs by the effect of FIRΔexon2 were examined in HCT116 cells." (PMID 38139171, 2023).
meningioma (1 paper, 2011). A generally slow growing tumor attached to the dura mater. "NormFinder and Bestkeeper-1 identified RPL37A as the most stable expressed gene in meningiomas and their normal control tissue." (PMID 21806841, 2011). "Both algorithms considered RPL37A as the most suitable reference gene for normalization in qPCR in meningiomas and their control tissue." (PMID 21806841, 2011). "RPL37A is the optimal single reference gene for normalization of gene expression in meningiomas and their control tissues, although the use of the combination of RPL37A and EIF2B1 would provide more stable results." (PMID 21806841, 2011). "Both algorithms identified RPL37A as the most stable gene in meningiomas and normal control tissue with an average expression stability value (M) value of 0.54 (Bestkeeper-1) respectively 0.12 (NormFinder)." (PMID 21806841, 2011). "For meningiomas and their normal control tissue the combination is RPL37A and EIF2B1." (PMID 21806841, 2011). "In conclusion, the results from the current study demonstrate that RPL37A is the most appropriate single reference gene for the normalization process of gene profiling studies in meningiomas and their normal control tissue arachnoidea, dura mater and normal brain." (PMID 21806841, 2011). "Eight highest ranked reference genes (CASC3, EIF2B1, IPO8, MRPL19, PGK1, POP4, PPIA, and RPL37A) plus GAPDH and ACTB were then analyzed in 35 meningiomas, arachnoidea, dura mater and normal brain." (PMID 21806841, 2011).
tuberculosis (1 paper, 2017). A chronic, recurrent infection caused by the bacterium Mycobacterium tuberculosis. "In a study based on microarray data, among several other genes, RPL37A was found to be suitable for normalizing RT-qPCR data in whole blood from tuberculosis patients." (PMID 28777335, 2017).
cancer (5 papers, 2016 to 2022). A tumor composed of atypical neoplastic, often pleomorphic cells that invade other tissues. "On the other hand, decreased 60S ribosomal protein L37a (RPL37A) in irradiated MSC was in line with common suppression in distinct cancers." (PMID 34072546, 2021).
tumor (5 papers, 2012 to 2025). "We observed significant downregulation of SOX7 expression in MM bone marrow tumor samples compared to normal bone marrow PC samples when expression levels of RPL37A or EMC7 housekeeping gene were used to obtain normalized expression of each sample." (PMID 40699642, 2025).
RPL37A also shares sentences with these, for which no sentence is quoted: adenoma (1 paper); astrocytomas (1); lung carcinoma (1); macrosomia (1); nasopharyngeal carcinoma (1); non-alcoholic fatty liver disease (1); ovarian mucinous adenocarcinoma (1); polycystic ovary syndrome (1); tauopathies (1).